CENPF (centromere protein F)
Diseases named in the same sentence as CENPF in open-access papers (continued):
Sharing a sentence is not in itself a finding about the gene and the disease.
cervical carcinoma (7 papers, 2016 to 2025). A carcinoma arising from either the exocervical squamous epithelium or the endocervical glandular epithelium. "Knocking down CENPF caused ferroptosis to happen in the cervical cancer cells by inhibiting the Nrf2/HO-1 signaling axis." (PMID 38536579, 2024). "In the first place, an analysis of the GEPIA database revealed an elevated expression of CENPF in human cervical cancer tissues and cell lines." (PMID 38536579, 2024). "We conducted immunohistochemistry and western blot analysis to examine the expression levels of CENPF in both cervical cancer tissues and cells." (PMID 38536579, 2024). "In this paper, we discovered that striking overexpression of CENPF in cervical cancer tissues compared to ordinary cervix." (PMID 38536579, 2024). "According to bioinformatics research, CENPF serves as a master regulator that is upregulated and activated in cervical cancer." (PMID 38536579, 2024). "For further research into the character of CENPF in cervical cancer, we used shRNA to construct knockout genes in HeLa cells and SiHa cells and identified that CENPF protein levels were decreased in both cell lines compared to the Sh-NC group." (PMID 38536579, 2024). "The ferroptosis induced by CENPF inhibition in cervical cancer cell lines is likely mediated through the Nrf2/HO-1 pathway." (PMID 38536579, 2024). "Taken together, the knocking down of CENPF restrained the malignant potential of cervical carcinoma cells by restraining the Nrf2 signaling axis." (PMID 38536579, 2024). "The data herein come up with the opinion that CENPF may have a crucial role in influencing anti-cervical cancer effects by inducing ferroptosis via the triggering of the Nrf2/HO-1 signaling pathway." (PMID 38536579, 2024). "Thus, CENPF is a hopeful therapeutic molecular target for cervical cancer that it is necessary to conduct further research." (PMID 38536579, 2024). "However, little is known regarding the expression levels and function of CENPF in cervical cancer, or its mechanism of action." (PMID 38536579, 2024). "The aim of this study was to analyze the function of CENPF on cervical cancer and its mechanism." (PMID 38536579, 2024). "CENPF is a potentially applicable candidate for diagnosing and treating cervical cancer." (PMID 35409038, 2022). "However, the expression patterns, molecular mechanisms, and biological functions of CENPF in cervical cancer are not well explained." (PMID 38536579, 2024).
adrenocortical carcinoma (5 papers, 2017 to 2025). "The CDK1-interacting protein CENPF has been found to be over-expressed in human adrenocortical carcinoma samples in correlation with tumor stage and poor overall survival (OS)." (PMID 36266723, 2022). "Further exploration of the GO enrichment analysis revealed that CENPF functions in the cell cycle through regulating mitosis and microtubule binding in various cancers, for instance, CENPF contributes to the deterioration of adrenocortical carcinoma by affecting the cell cycle." (PMID 37108172, 2023).
ovarian carcinoma (5 papers, 2018 to 2022). A malignant neoplasm originating from the surface ovarian epithelium. "The depletion of CENPE and CENPF has been related to the significant disruption of the cell cycle and paclitaxel resistance in ovarian cancer." (PMID 35496042, 2022). "In one previous study, 4 of 16 identified hub genes in the studied sample (CCNB1, CENPF, KIF11, and ZWINT) were associated with decreased OS of patients with ovarian cancer." (PMID 34785763, 2022). "Our study revealed gene depletion across a number of molecular components involved in the spindle assembly checkpoint and mitotic regulation, including BUB1, CCNB1, CENPE and CENPF in paclitaxel resistant ovarian cancer cell lines." (PMID 29618387, 2018). "The gene encoding this protein, ZWINT, was discovered to be overexpressed in ovarian cancer, among other genes (such as CCNB1, CENPF, KIF11) related with cell cycle, nuclear division and oocyte meiosis." (PMID 33445445, 2021).
Strømme syndrome (5 papers, 2019 to 2023). "In 2015, CENPF null alleles were shown to cause Strømme syndrome (OMIM 243605) with autosomal recessive inheritance." (PMID 38002928, 2023). "We describe three unrelated patients with clinical features of Strømme syndrome and bi-allelic variants in CENPF." (PMID 38002928, 2023). "In summary, the two CENPF variants in patient 3 were classified as pathogenic and considered causative of the Strømme syndrome." (PMID 38002928, 2023). "The two CENPF variants were classified as pathogenic and considered causative of the Strømme syndrome." (PMID 38002928, 2023). "Strømme syndrome is an ultra-rare primary ciliopathy with only 18 families previously reported with documented bi-allelic pathogenic variants in CENPF." (PMID 38002928, 2023). "We report three unrelated patients with Strømme syndrome and, using high-throughput sequencing approaches, we identified novel pathogenic variants in CENPF, including one structural variant, giving a genetic diagnosis to the patients." (PMID 38002928, 2023). "Most patients with a molecular diagnosis carry null alleles, but more recently five independent patients with missense variants in CENPF and Strømme syndrome were reported, possibly with a milder phenotype, as they did not present with intestinal atresia and eye anomalies." (PMID 38002928, 2023). "However, the second variant was identified only after implementation of a LR-WGS approach, which allowed us to detect a structural variant on the other CENPF allele, and thus concluding the molecular diagnosis of Strømme syndrome." (PMID 38002928, 2023). "The clinical manifestations in patient 3 in the present study were compatible with a diagnosis of Strømme syndrome, and the WES analysis identified a heterozygous pathogenic variant in CENPF." (PMID 38002928, 2023). "The deleted genomic region in patient 3 overlapping CENPF exon 1 may be a site of a recurrent structural variation and should be investigated carefully in patients with a clinical diagnosis of Strømme syndrome." (PMID 38002928, 2023). "CENPF exon 1 is flanked by repetitive sequences that may represent a site of a recurrent structural variation, which should be a focus in patients with Strømme syndrome of unknown etiology." (PMID 38002928, 2023). "We report four patients with biallelic CENPF variants and three of them were lacking the complete clinical trial of Strømme syndrome." (PMID 35488810, 2022). "Moreover, these four cases differ from the recurrent pattern of abnormalities of Strømme syndrome, suggesting a broad spectrum of clinical manifestations for CENPF‐related disease." (PMID 35488810, 2022). "Therefore, structural variants affecting CENPF exon 1 should be carefully analyzed in patients with a clinical diagnosis of Strømme syndrome but lacking a molecular diagnosis." (PMID 38002928, 2023). "In addition, patients with phenotypes compatible with Strømme syndrome, but without identified pathogenic variants in CENPF, have been reported before the genetic basis was discovered." (PMID 38002928, 2023). "This case‐series of individuals with biallelic CENPF variants suggests the spectrum of clinical manifestations of the disorder that may be related to CENPF variants is broad and can include phenotypes lacking the cardinal features of Strømme syndrome." (PMID 35488810, 2022).
breast tumors (4 papers, 2008 to 2020). "It has been previously reported that CENPF is highly expressed in breast tumors of patients with poor prognosis and is associated with proliferation in different human malignancies." (PMID 22912832, 2012). "Through GDS5306 analysis, published datasets consisting of 19 brain metastasis specimens and matched primary breast tumor specimens of 19 BC patients, we also found that the mRNA expression of CENPF does not differ between primary breast tumors and brain metastasis tissue." (PMID 31632198, 2019).
cutaneous melanoma (4 papers, 2021 to 2025). A primary melanoma arising from atypical melanocytes in the skin. "Our results revealed several novel biomarkers and biological pathways that participate in the pathogenesis of cutaneous melanoma, and demonstrated the diagnostic and prognostic value of CDC45, CENPF, DTL, FANCI, GINS2, HJURP, TPX2 and TRIP13." (PMID 33531976, 2021). "In addition, studies have found that CENPF is positively associated with CD4+ memory T-cell phenotypic markers and negatively correlated with memory T-cell survival regulators in cutaneous melanoma." (PMID 36644760, 2022).
esophageal cancer (4 papers, 2019 to 2022). A primary or metastatic malignant neoplasm involving the esophagus. "Interestingly, there is evidence that CENPF expression is associated with inferior outcomes in patients with esophageal cancer and patients with lower CENPF expression had a better survival rate compared with those with higher CENPF expression." (PMID 33828156, 2021). "Three hub targets were retrieved, including CENPF, CCNA2 (cyclin A), and CCNB1 (cyclin B1), which were highly expressed in esophageal cancer and associated with prognosis." (PMID 35484963, 2022). "Studies have shown that the expression levels of CDCA3 and CENPF are correlated in esophageal carcinoma." (PMID 34905505, 2021). "Among these genes, MAD2L1 and CENPF are oncogenes in esophageal carcinoma." (PMID 30716092, 2019). "We noted that compared to normal tissue, BIRC5, CENPF, STMN1, APOC2, and HNRPC were the five most significantly upregulated genes in esophageal cancer." (PMID 33828156, 2021). "The comparison between esophageal tumors and healthy tissue showed BIRC5 (p = 2.61E−08), APOC2 (p = 3.23E−08), CENPF (p = 4.38E−08), STMN1 (p = 5.74E−08), and HNRPC (p = 8.21E−08) to be five leading genes overexpressed in esophageal cancer." (PMID 33828156, 2021).
intestinal atresia (4 papers, 2019 to 2023). A congenital malformation characterized by the absence of a normal opening in a part of the intestine. "Patient 2, a female patient primarily affected by intestinal atresia, was compound heterozygous for CENPF NM_016343.3:c.5920dup, p.(Thr1974Asnfs*9) and NM_016343.3:c.8991del, p.(Ser2998Alafs*23), both causing frameshifts." (PMID 38002928, 2023). "CENPF can also be considered as a biomarker of fetal intestinal atresia for prenatal diagnosis." (PMID 33344459, 2020).
Cirrhosis (3 papers, 2021 to 2022). A chronic disorder of the liver in which liver tissue becomes scarred and is partially replaced by regenerative nodules and fibrotic tissue resulting in loss of liver function. "Consistent with the results, CENPF was found to be significantly upregulated in cirrhosis, liver cell dysplasia and HCC tumors compared with normal livers." (PMID 33854594, 2021). "This study revealed that PRC1, RACGAP1, CENPF, and CCNB2 could sensitively distinguish HCCfrom cirrhosis, and they may be potential targets for early HCC detection." (PMID 35445033, 2022). "Compared with that in normal livers, CENPF was evidently upregulated in HCC tumors (P < 0.001), but not in cirrhosis, and liver cell dysplasia (P > 0.05)." (PMID 33854594, 2021).
COVID-19 (3 papers, 2022 to 2024). A disease caused by infection with severe acute respiratory syndrome coronavirus 2. "This analysis revealed a pattern of gene expression in microglia from patients with COVID-19 that included a nearly complete downregulation of genes associated with cellular proliferation (MKI67, CENPF) and upregulation of the cell cycle arrest marker CDKN1A (encoding p21)." (PMID 38502186, 2024). "Further studies are needed to investigate the effect of targeting CENPF and CIT as a possible therapeutic strategy to treat COVID-19." (PMID 35831333, 2022). "In the study of tissue regeneration after acute injury, we analyzed the database of ALF and COVID-19 by bioinformatics method and found common hub genes, including CDC20, CENPF, KIF4, KIF11, NUSAP1, TPX2, and PTTG1, which were related to mitosis and cell cycle regulation." (PMID 36911196, 2023).
glioblastoma (3 papers, 2016 to 2023). The most malignant astrocytic tumor (WHO grade IV). "However, Pin1 expression does not appear to significantly correlate with FOXM1, CENPF and Cyclin B1 expression in at least mammary, ovarian, renal and endometrial carcinomas and glioblastoma, suggesting the regulation of FOXM1 activity by Pin1 might be restricted to subsets of cancers." (PMID 26279295, 2016).
cervical squamous cell carcinoma (2 papers, 2020 to 2024). A squamous cell carcinoma arising from the cervical epithelium. "However, cervical squamous cell carcinoma and endocervical adenocarcinoma (CESC) is one of the several cancer types (8 and 4 for TOP2A and CENPF, respectively) which showed most significant expression increase (ANOVA P < 1E-10 and fold change> 4) in tumor compared to normal tissues." (PMID 33023625, 2020).
colon cancer (2 papers, 2012 to 2019). "Of these, the following four genes were common to both HCC and colon cancer: CENPF, GMNN, CDK13, and FAM82B." (PMID 22912832, 2012). "For example, the altered phosphorylation of CENPF affected glutamine uptake in colon cancers." (PMID 31850052, 2019).
endometrial carcinoma (2 papers, 2016 to 2024). A malignant tumor arising from the epithelium that lines the cavity of the uterine body. "Within this network, 100 DEGs were found, and three genes (BIRC5, CENPF, HJURP) overlapping with DEM targets were associated with worse overall survival in endometrial cancer." (PMID 39108650, 2024).
lymphoma (2 papers, 2022 to 2026). A malignant (clonal) proliferation of B- lymphocytes or T- lymphocytes which involves the lymph nodes, bone marrow and/or extranodal sites. "Then, immunohistochemical staining of CENPF in lymphoma tissue was also performed to evaluate the expression and distribution of CENPF in CR patients and RR patients." (PMID 36644760, 2022).
Obesity (2 papers, 2022). Accumulation of substantial excess body fat. "In the present study, growth-related genes, GAL, CENPF, and GPC2, obesity-related gene, PEMT, and CYP3A4, P450, TMEM200B genes were found to be associated with BWF." (PMID 35795788, 2022). "Several hub genes, such as TOP2A, CENPF, TYMS, AURKA, KIF4A, and KIF20A, are related to the cell cycle and DNA replication, implicating the close relationship between obesity and cancer." (PMID 36232337, 2022).
small cell lung carcinoma (2 papers, 2021 to 2022). Small cell lung cancer (SCLC) is a highly aggressive malignant neoplasm, accounting for 10-15% of lung cancer cases, characterized byrapid growth, and early metastasis. "The result showed that small cell lung cancer and the ErbB signalling pathway were obviously enriched in CENPF high expression phenotype." (PMID 35154456, 2022). "The results showed that CENPF was upregulated in the LUAD cell lines (A549 and H1299) compared with that in small cell lung cancer cell lines (H446 and H69)." (PMID 33390818, 2021).
thyroid cancer (2 papers, 2023 to 2024). "Immunohistochemistry results show abnormal expression of proteins such as FKBP5, CENPF, CX26, KIF11, PTK7, which are associated with poor prognosis in thyroid cancers with intraglandular dissemination, offering potential guidance for specific targeted therapy in the future." (PMID 39135992, 2024). "Furthermore, cell experiments have shown that silencing CENPF can inhibit proliferation, induce cell cycle arrest, and promote apoptosis in thyroid cancer cells (thyroid cancer cells:TPC-1 and KTC-1 cell lines)." (PMID 39135992, 2024). "CENPF is already known as thyroid carcinoma biomarker, involved in migration and proliferation." (PMID 37191407, 2023).
ZIKV infection (2 papers, 2017 to 2021). "Dysregulation of the neuronal genes, such as RBBP8, ASPM, AXL, TBR2, MCPH1, and CENPF upon ZIKV infection may cause different neurological or brain development related disorders." (PMID 33891593, 2021).
adrenocortical adenoma (1 paper, 2022). "Thus, it suggested that CENPF could be viewed as a biomarker to make a distinction between ACC and adrenocortical adenoma or normal adrenal cortex tissues." (PMID 35123514, 2022).
alcohol- (1 paper, 2021). "In the future research, we need explore the exact molecular mechanisms of these immune cells in alcohol-related HCC and learned whether CENPF and BUB1B can affect the development of alcohol-related HCC through the regulation of immune cells." (PMID 34646769, 2021).
Arrhythmia (1 paper, 2018). Any cardiac rhythm other than the normal sinus rhythm. "With cardiac specific deletion of Centromere Protein F (CENP-F), a protein known to interact with microtubules, the resulting animals exhibited enlarged ventricles with thinner walls, fewer trabeculae, increased fibrosis, and arrhythmia (all hallmarks of DCM), as well as death in 20% of outcomes." (PMID 29765066, 2018).
atherosclerosis (1 paper, 2019). A disease characterized by the build-up of fatty material and calcium deposition in the arterial wall resulting in partial or complete occlusion of the arterial lumen. "To interrogate the SMILR:CENPF:STAU1 interaction in human atherosclerosis, we performed an RNA-seq on relatively stable and unstable regions dissected from fresh human carotid plaques obtained at carotid endarterectomy in symptomatic patients." (PMID 31339449, 2019).
atopic dermatitis (1 paper, 2022). "Cell cycle transcripts, which are elevated in both psoriasis and atopic dermatitis Trm2 compared to healthy controls, also show higher than median dispersion scores, including MKI67 (0.358), TOP2A (0.276), and CENPF (0.356)." (PMID 35958578, 2022).
colorectal tumors (1 paper, 2025). "Consistently, findings indicated upregulation of both CENPF mRNA and protein in colorectal tumors compared to adjacent normal tissues." (PMID 39922805, 2025).
cryptorchidism (1 paper, 2022). The failure of one or both testes of a male fetus to descend from the abdomen into the scrotum during the late part of pregnancy. "Consistently, patients carrying CENPF variants have been found to have kidney malformations and end‐stage renal disease and most cases in our series showed genitourinary malformations including horseshoe kidney, ureteral defects, and cryptorchidism." (PMID 35488810, 2022).
esophageal tumors (1 paper, 2021). "The stage-based assessment of overexpressed genes showed significant overexpression of BIRC5, APOC2, CENPF, STMN1, and HNRPC across all cancer stages including early, locally advanced and metastatic esophageal tumors." (PMID 33828156, 2021).
follicular lymphoma (1 paper, 2015). Follicular lymphoma is a form of non-Hodgkin lymphoma characterized by a proliferation of B cells whose nodular structure of follicular architecture is preserved. "The other genes, such as HK2, CENPF, CTPS, LDHA, P2RY5 and DNASE1L3 also can be identified in both transformation follicular lymphoma and ‘indolent’ type FL." (PMID 26416427, 2015).
holoprosencephaly (1 paper, 2025). Holoprosencephaly (HPE) is a complex brain malformation resulting from incomplete cleavage of the prosencephalon, occurring between the 18th and 28th day of gestation, and affecting both the forebrain and face, which results in neurological manifestations and facial anomalies of variable severity. "Other gene mutations that relates to holoprosencephaly, including ZIC2, SIX3, TGIF1, CDON, FGFR1, CENPF and DHCR7, were not identified." (PMID 39859210, 2025).